SALL1 (spalt like transcription factor 1)
Diseases named in the same sentence as SALL1 in open-access papers (continued):
Sharing a sentence is not in itself a finding about the gene and the disease.
renal hypoplasia (2 papers, 2014 to 2019). Renal hypoplasia is a developmental anomaly in which one or both kidneys (unilateral or bilateral renal hypoplasia, respectively) have a deficit in the number of nephrons and may be small. "A wide variety of SALL1 mutations were observed in all foetuses, and a nephrogenic defect or severe renal hypoplasia was observed in nine (69.2%)." (PMID 31142767, 2019). "The involvement of affiliated genes in the phenotypic variation in renal hypoplasia following SALL1 knockout has yet to be determined." (PMID 31142767, 2019). "Studies into cases of ‘non-syndromic’ renal hypoplasia have identified mutations in several key genes which include PAX2, SIX2, BNP4, SALL1, UMOD and TCF2." (PMID 24886545, 2014).
Stroke (2 papers, 2021 to 2024). Sudden impairment of blood flow to a part of the brain due to occlusion or rupture of an artery to the brain. "Similarly, in two stroke models, macrophages infiltrating the CNS or ectopically placed in peri-infarct areas, became TMEM119+ and/or P2RY12+ and/or Sall1+." (PMID 34311763, 2021).
adenoma (1 paper, 2010). A neoplasm arising from the epithelium. "SALL1 was methylated in 83% of CRC and in 89% of adenomas, whilst methylation frequency in corresponding normals was much less (38%)." (PMID 20205715, 2010).
amyotrophic lateral sclerosis (1 paper, 2018). Amyotrophic lateral sclerosis (ALS) is a neurodegenerative disease characterized by progressive muscular paralysis reflecting degeneration of motor neurons in the primary motor cortex, corticospinal tracts, brainstem and spinal cord. "It was shown that microglia uniformly downregulate their homeostatic signature genes, such as Sall1, Pu.1, Tmem119, Cx3cr1, and P2ry12/13 and upregulate risk genes for AD, such as Apoe and Trem2, in mouse models for aging, AD (5XFAD and APP-PS1), and amyotrophic lateral sclerosis (ALS) (SOD1)." (PMID 30108586, 2018).
atherosclerosis (1 paper, 2016). A disease characterized by the build-up of fatty material and calcium deposition in the arterial wall resulting in partial or complete occlusion of the arterial lumen. "In addition, we evaluated the potential relationship between HNF1A rs1183910, LEPR rs4420065, GCKR rs1260326, NLRP3 rs12239046, IL1F10 rs6734238, PPP1R3B rs9987289, ASCL1 rs10745954, HNF4A rs1800961 and SALL1 rs10521222 polymorphisms and CV events or subclinical atherosclerosis in RA patients." (PMID 27534721, 2016).
atopic dermatitis (1 paper, 2022). "SALL1 was the nearest gene to rs11648772, and its RNA expression was associated with airway wall thickness in asthmatic patients with atopic dermatitis." (PMID 35886039, 2022).
Blindness (1 paper, 2013). Blindness is the condition of lacking visual perception defined as a profound reduction in visual perception. "We identified the first homozygous SALL1 mutation, c.3160C > T (p.R1054*), in 2 female siblings presenting with multiple congenital anomalies, central nervous system defects, cortical blindness, and absence of psychomotor development (ie, a novel recognizable, autosomal recessive MCA-MR)." (PMID 23069192, 2013).
Branchio-oculo-facial syndrome (1 paper, 2024). "Not only KBG syndrome but also Townes–Brocks syndrome caused by SALL1 variants and branchio-oculo-facial syndrome (BOFS) caused by TFAP2A variants show pheno-typic overlap with BOR/BO syndrome." (PMID 39125727, 2024).
DiGeorge syndromes (1 paper, 2016). "These syndromes mainly include Townes–Brocks (SALL1), CHARGE (CHD7), Fraser (FRAS1), and DiGeorge syndromes (del22q11)." (PMID 28003020, 2016).
dysplasia (1 paper, 2009). A usually neoplastic transformation of the cell, associated with altered architectural tissue patterns. "Genetic targeting of mouse SALL1 results in severe renal dysplasia or complete agenesis, indicating that SALL1 plays an essential role in early kidney development." (PMID 19440552, 2009).
fractures (1 paper, 2022). "The signals in the other four genomic loci associated with hip fractures (REST, HOXC8, SALL1, and ETS2) were previously shown to associate with different BMD measures, supporting the notion that BMD is an important determinant also of hip fracture risk." (PMID 36260985, 2022).
glaucoma (1 paper, 2012). Increased pressure in the eyeball due to obstruction of the outflow of aqueous humor. "Of these, only the CDKN2BAS and SIX1/SIX6 regions were significantly associated with glaucoma in the meta-analysis, although several other previously identified gene regions demonstrated suggestive associations including SALL1, LRP1B and SIRPA." (PMID 22570617, 2012).
Goldenhar syndrome (1 paper, 2015). "Here, the patient was suspected to have Goldenhar syndrome, but in light of a mutation in the SALL1 gene, and the re-evaluation of the patient phenotype, the diagnose was changed." (PMID 26380986, 2015).
Hydrocephalus (1 paper, 2020). Hydrocephalus is an active distension of the ventricular system of the brain resulting from inadequate passage of CSF from its point of production within the cerebral ventricles to its point of absorption into the systemic circulation. "A maternally-inherited frameshift variant in SALL1 was identified in an ARM-PLUS patient with a perineal fistula, atrial septal defect, agenesis of the septum pellucidum, right single transverse palmar crease, flat feet, and postnatal cerebral hemorrhage leading to hydrocephalus (ID = 2)." (PMID 32656166, 2020).
hypospadias (1 paper, 2022). Hypospadias is the displacement of the urethral meatus on the ventrum of the penis. "Two patients (patients 1 and 6) carried SALL1 and SPECC1L mutations at the same time, which are involved in syndromes including hypospadias, but the role of these two mutations in the two patients may need to be further studied." (PMID 35669683, 2022).
Intellectual disability (1 paper, 2025). "Another patient (SC1136) with a SALL1 frameshift variant presented with a TBS1 phenotype and intellectual disability." (PMID 40658219, 2025).
melanoma (1 paper, 2018). A malignant, usually aggressive tumor composed of atypical, neoplastic melanocytes. "We observed markedly elevated SALL1 gene expression in all melanoma cell lines and moderate gene expression in normal fibroblasts and 293 T cells." (PMID 29625565, 2018). "In addition, we did not observe increased senescent cell populations in melanoma B16F0 cells after over-expression of SALL1." (PMID 29625565, 2018). "However, over-expression of SALL1 in B16F0 melanoma cells, and normal breast cell MCF12A did not affect cell growth and proliferation." (PMID 29625565, 2018). "Notably, transfection of SALL1 in melanoma B16F0 cells induced neither cell apoptosis nor cell cycle arrest." (PMID 29625565, 2018).
microphthalmia (1 paper, 2009). Congenital or developmental anomaly in which the eyeballs are abnormally small. "It is reported that microphthalmia is two to five times more common in twins than in singletons, which limits the utility of this case in assigning causality of the microphthalmia in this pair of twins to the SALL1 mutation." (PMID 20003547, 2009). "As this patient has not be characterized molecularly and is now deceased (A.R. Cooper, personal communication), we cannot determine if that child had microphthalmia and TBS because of a 16q deletion or that s/he had a point mutation in SALL1 and microphthalmia is a rare manifestation of TBS." (PMID 20003547, 2009). "Microphthalmia has been reported in a pair of twins with TBS and a point mutation in SALL1 and a patient from the pre-molecular era with a clinical phenotype consistent with TBS." (PMID 20003547, 2009).
microtia (1 paper, 2022). "One significant gene–gene interaction related to the presentation of microtia/OAVS was identified: that between the non-synonymous p.(Pro1099Arg) TCOF1 variant and the synonymous p.(Leu858=) SALL1 variant." (PMID 36362878, 2022).
myopia (1 paper, 2010). "However, in our analyses we could not find evidence for an association of the common SNPs in the SALL1 region to myopia (rs1362756; p = 0.802)." (PMID 20548946, 2010).
neural tube defect (1 paper, 2024). A congenital defect characterized by failure of the neural tube to close completely; this results in the presence of openings in the brain or spinal cord. "Sall2 deficient mice may exhibit neural tube defect (NTD), depending on the genetic background, while compound deletion of Sall1, Sall2, and Sall4 led to more severe NTD, implying functional redundancy among Sal family members." (PMID 39349437, 2024).
ovarian tumors (1 paper, 2023). "SALL1 misexpression has also been linked to certain types of androgen-producing ovarian tumors, indicating that it might be involved in re-programming ovarian cells." (PMID 37519269, 2023).
Pendred syndrome (1 paper, 2023). Pendred syndrome (PDS) is a clinically variable genetic disorder characterized by bilateral sensorineural hearing loss and euthyroid goiter. "A genetic cause was found for both subjects (Townes–Brocks syndrome (SALL1) and Pendred Syndrome (SLC26A4))." (PMID 36675424, 2023).
renal cell cancers (1 paper, 2018). "There is only limitted information about SALL1’s role in cellular signaling and transcriptional regulation apart from the few described in embryonic development and in breast and renal cell cancers." (PMID 29484122, 2018).
ZIKV infection (1 paper, 2022). "The basal level of expression of the Sall1 gene was significantly lower in CC071 as compared to CC001 mice and remained so after ZIKV infection." (PMID 36539803, 2022).
tumor (26 papers, 2009 to 2026). "We observed that E0771 tumor cells alone or transfected with mutated SALL1 gene or vector control, grew progressively in NSG mice." (PMID 29625565, 2018). "Of these, heart and neural crest derivatives expressed 2 genes (HAND2 and SALL1) reported to be hypermethylated and associated with tumorigenesis in tumor tissues." (PMID 30237858, 2018). "As expected, we observed that transferred E0771 tumor cells alone or transfected with mutated SALL1 gene or vector control, grew significantly with metastasis/colonization in lungs and livers." (PMID 29625565, 2018). "Whether Gbx2 is associated with the tumor suppressor function of SALL1 is currently unknown." (PMID 34944911, 2021). "By contrast, SALL1, a microglial lineage-determining and homeostatic gene, decreased with tumor grade 30." (PMID 38895459, 2025). "In this regard, SALL1 acts as a tumor suppressor by recruiting nucleosome remodeling and deacetylase complex to trigger tumor cell senescence in BC30." (PMID 38802425, 2024). "KIF26B is a downstream target of the zinc finger protein Sall1, which is involved in the development of various tumours." (PMID 35292033, 2022). "In support of such a tumor suppressor role, Sall1 has been found to be a target of oncogenic miRNAs." (PMID 34195082, 2021). "On the other hand, SALL1 downregulation has been described in cerebral glioma tissues, correlating with higher tumor grade and lower survival." (PMID 34944911, 2021). "In cancer, Sall1 has been found to be downregulated in breast cancer, glioblastoma, and myeloid leukemia, supporting its role as a tumor suppressor." (PMID 34195082, 2021). "In summary, SALL1 functions as a putative tumor suppressor in GBM, but SALL2 and SALL4 are crucial for tumor development and progression, which is associated with PI3K/AKT pathway activation and the maintenance of an undifferentiated aggressive phenotype." (PMID 34944911, 2021). "Tumor suppression was mediated by recruitment of NuRD complex with SALL1 and by releasing of this complex from chromatin, cancer cells can be rescued from cell senescence." (PMID 31040906, 2019). "Our studies revealed that tumor suppression was mediated by recruitment of the Nucleosome Remodeling and Deacetylase (NuRD) complex by SALL1, which promoted cancer cell senescence." (PMID 29625565, 2018). "In contrast, transfection of SALL1-S2A into tumor cells significantly augmented senescence induction in both cell lines compared with that of wild type SALL1-transfected tumor cells." (PMID 29625565, 2018). "We demonstrated that SALL1 can induce tumor cell senescence as a novel mechanism of tumor suppressor function." (PMID 29625565, 2018). "We further revealed that SALL1 tumor suppressor activity depended on its ability to recruit NuRD and that this molecular process was controlled by MAPK p38 and ERK1/2, and mTOR signaling pathways in cancer cells." (PMID 29625565, 2018). "MDA-MB-231 tumor cells were transfected with SALL1 for 72 h and then RT-PCR for gene expressions was performed." (PMID 29625565, 2018). "Mouse E0771 and B16F0 tumor cells infected with Lentivirus carrying SALL1, mSALL1 or vector, were subcutaneously injected into NSG mice." (PMID 29625565, 2018). "Using the gain-of function and loss-of-function strategies, we dissected the molecular mechanism responsible for SALL1 tumor suppressor functions." (PMID 29625565, 2018). "We then used shRNAs to specifically knock down p38 and ERK1/2 genes in MCF-7 and E0771 cells, and measured the effects on SALL1-induced tumor cell senescence." (PMID 29625565, 2018). "SALL2 and SALL4 have been recently recognized as regulators of tumorigenesis, but little information is known about the role of the SALL1 gene in regulation of tumor biology." (PMID 29625565, 2018). "Dissection of the unique molecular signaling responsible for SALL1-mediated tumor suppression is another challenge." (PMID 29625565, 2018).
tumor (continued). "In contrast, transfection of SALL1 in E0771 cells dramatically decreased tumor macro-metastatic numbers both in lung and in liver surfaces." (PMID 29625565, 2018). "Down-regulation was seen for CNTN1, CXCL13, MAOB, PAGE4, PENK, SPOCK3 in CP compared to NP as well as for HSD17B2, SALL1, TRPA1 for tumor-associated bladder stromal cells compared to normal bladder." (PMID 19737398, 2009). "Moreover, SALL1-knockdown SUM149 cells xenografted into immunodeficient NSG mice resulted in a significantly decreased tumor-free survival." (PMID 34944911, 2021). "Moreover, SALL1 and SALL2 act as tumor suppressors and are associated with proliferation arrest, ESR1 expression, and good prognosis." (PMID 34944911, 2021). "Most cancer studies relate SALL4 to an oncogenic function and SALL1–3 to a tumor suppression role; still, there is evidence that SALL1 and SALL2 could play a dual role." (PMID 34944911, 2021). "SALL1 action as a tumor suppressor and epigenetic inactivation of this gene is responsible for development of cancer, but this gene might be liable for pituitary prolactinoma." (PMID 33709028, 2021). "Importantly, the tumor suppressor function mediated by SALL1 is mechanistically related to cell senescence induction via the recruitment of the NuRD complex in cancer cells." (PMID 29625565, 2018). "In addition, the loss-of-function studies with specific pharmacological inhibitors and lentivirus-based shRNAs further indicated that SALL1-mediaed tumor suppression and senescence induction is controlled by both MAPK and mTOR signaling pathways." (PMID 29625565, 2018). "MCF7 and E0771 tumor cells were transfected with SALL1 for 24 h and then RT-PCR was performed." (PMID 29625565, 2018). "SALL1 is a multi-zinc finger transcription factor that regulates organogenesis and stem cell development, but the role of SALL1 in tumor biology and tumorigenesis remains largely unknown." (PMID 29625565, 2018). "Further dissection of how MAPK signaling and mTOR signaling cooperate and identification of unique adaptor molecules controlling SALL1 biological functions in tumor cells will be critical preludes for the application of SALL1 and tumor senescence as new targets for tumor therapeutic interventions." (PMID 29625565, 2018). "Suppression of tumor cell proliferation and growth mediated by SALL1 expression could be due to the induction of apoptosis or cytolysis in the tumor cells." (PMID 29625565, 2018). "Mouse E0771 tumor cells infected with or without lentivirus carrying SALL1 or control mutated SALL1 gene were labeled with VivoTag®680 XL and then injected intravenously into the tail vein of NSG mice." (PMID 29625565, 2018). "We then investigated whether over-expression of SALL1 affected tumor metastasis using previously established adoptive transfer tumor models with a live imaging system." (PMID 29625565, 2018). "To test whether SALL1 is a tumor suppressor, we determined the effect on cancer cell growth and function by SALL1." (PMID 29625565, 2018). "Additionally, Zhang and collaborators identified SALL1 and SALL3 as part of a high-risk group of genes differentially expressed within a vast number of genes whose methylation status also differed when comparing tumor and adjacent normal tissue." (PMID 34944911, 2021). "However, how and whether Gbx2 and HDAC involve SALL1-mediated tumor cell DNA damage and senescence is still unknown in the current study." (PMID 29625565, 2018). "However, the signal density from the tumor cells transfected with SALL1 markedly decreased in the late time points (after 3 days) post tumor cell injection, suggesting the lower capacity of tumor metastasis and/or colonization compared with that of the other groups." (PMID 29625565, 2018). "Knockdown of SALL1 in the HCC cell lines Huh7 and Hep3B, enhanced cell proliferation in vitro and accelerated tumor growth in a xenograft mouse model, suggesting that lower SALL1 expression increases cell proliferation and tumorigenesis in HCC." (PMID 42122151, 2026).
tumor (continued). "Tumor specimens exhibited elevated expression of DTX2, SALL1, ZNF93, ZNF146 and ZSCAN16, contrasting with reduced levels of EGR2, GATA2, and ZEB2." (PMID 40647501, 2025). "In oral squamous cell carcinoma (OSCC), SALL2 promoter hypermethylation positively correlates with SALL1 and SALL3 promoter methylation status and aggressive tumor behavior." (PMID 34944911, 2021). "Expression of wild type SALL1 and SALL1-S2A in MCF-7 tumor cells recruited the endogenous NuRD complex components." (PMID 29625565, 2018). "We observed that transfection of SALL1 in MCF-7, MDA, and E0771 tumor cells significantly increased the number of SA-β-Gal+ cells, indicating the induction of tumor cell senescence." (PMID 29625565, 2018). "Five genes (62.5%) demonstrated tumour acquired methylation (EMILIN2, SALL1, DBC1, FBLN2 and CIDE-A), whilst the remaining 3 (COMP, EPSTI1, SIM2) showed equal methylation in the corresponding normal breast tissue DNA." (PMID 20205715, 2010). "Notably, genes such as NRG1, SAMD13, MFAP3L, SALL1, ZNF704, SEMA5A, and HLA-DQB1 were identified as having altered expression patterns, potentially reflecting the diverse roles of FGFRS in tumor biology." (PMID 39676867, 2024). "(C) H & E staining on sections from embedded liver tissues showed that high amount of tumor cells infiltrated into livers obtained from control groups (mSALL1 and vector), but not from the SALL1 transfection group." (PMID 29625565, 2018). "In vitro wound closure assays were utilized to determine the capacity of tumor cell migration after transfection with or without SALL1." (PMID 29625565, 2018). "Furthermore, we confirmed, using histological staining on sections from embedded liver and lung tissues that a high number of tumor cells infiltrated into livers and lungs obtained from control groups of mSALL1 and vector-transfected E0771, but not from the SALL1-transfected tumor group." (PMID 29625565, 2018). "Microglial markers SALL1, TMEM119, and P2RY12 were minimally expressed among tumor-infiltrating cells, suggesting that microglia did not highly infiltrate the brain metastases in this patient." (PMID 37209684, 2023). "We found that transfection of SALL1, but not SALL4 or vector in MCF-7, MDA-MB-231, E0771 and PC-3 tumor cells significantly inhibited cell growth and proliferation." (PMID 29625565, 2018).